RNU6-1220P (RNA, U6 small nuclear 1220, pseudogene)
Gene: Small nuclear RNA gene on chromosome 8 (78,398,515 to 78,398,622, reverse strand). Ensembl gene ENSG00000252935.
Homologues: Orthologues: chimpanzee U6 (99% identical), guinea pig U6 (70% identical), mouse Gm54971 (56% identical). Paralogues in human: RNU6-144P (76% identical), RNU6-1099P (74% identical), RNU6-836P (74% identical), RNU6-1060P (73% identical), RNU6-119P (73% identical), RNU6-145P (73% identical), RNU6-15P (73% identical), RNU6-211P (73% identical), RNU6-21P (73% identical), RNU6-333P (73% identical), RNU6-46P (73% identical), RNU6-522P (73% identical), and 1284 more.